CD4 (CD4 molecule)
Diseases named in the same sentence as CD4 in open-access papers (continued):
Sharing a sentence is not in itself a finding about the gene and the disease.
babesiosis (5 papers, 2018 to 2022). Babesiosis refers to a condition caused by microscopic parasites that infect the red blood cells. "This recruitment of CD4+ T cells to the spleen early after infection may be important, considering that this T cell population is associated with protection against Babesia infection." (PMID 36466866, 2022). "The mechanism(s) involved in the depletion of CD4+ and CD8+ T cells during Babesiosis are likely to be linked with molecular signaling pathways induced by the Babesia parasite orchestrating the infection." (PMID 33187270, 2020). "A lower percentage of CD3+ and CD4+ lymphocytes were found in complicated babesiosis cases, and a lower percentage of CD8+ T lymphocytes was identified in babesiosis compared to healthy dogs, suggesting the presence of functional immune suppression." (PMID 31038320, 2019). "Collectively, our findings provide novel evidence of the role of both bovine CD4+ and CD8+ T cell populations in bovine Babesiosis, as their depletion, seen during the challenge, leads to the development of acute babesiosis." (PMID 33187270, 2020). "Therefore, it has been proposed that vaccines that prime CD4+ T cells to produce IFN-γ could induce and provide protective immunity against Babesia infection." (PMID 35812841, 2022).
basal cell carcinoma (5 papers, 2018 to 2023). A carcinoma involving the basal cells. "By analyzing 16,194 CD4+ cells from scRNA-seq data of basal cell carcinoma (BCC) and immunotherapy response data, we revealed that the SC-2 CD4+ cells existed in the TME of BCC." (PMID 36049666, 2023). "CD4+CD25+Foxp3+ T-cells can be found intermingled with human basal cell carcinoma along with the TH2 cytokines IL-4 and IL-10." (PMID 34771569, 2021). "While the molecular pathway such as IL-12, basal cell carcinoma, estrogen receptor, Ephrin A, PIK3, CD8, CD4 and IGF1R were significantly inhibited." (PMID 34493740, 2021).
bone metastasis (5 papers, 2018 to 2023). Transfer of a neoplasm from its primary site to bones. "A low number of stromal CD4 TILs were significantly associated with bone metastasis and poor performance status (PS)." (PMID 36662367, 2023). "Additionally, the low number of stromal CD4 TILs was significantly linked to bone metastasis and poor PS (online only)." (PMID 36662367, 2023). "Next, we investigated the population of CD4+ T cells within the tumor immune microenvironment of bone metastasis." (PMID 35948516, 2022). "We observed a decrease in both CD4 + T cells and CD8 + T cells in bone metastasis compared with primary sites and without a significant change in the CD4 + /CD8 + ratio." (PMID 36915210, 2023).
brain cancer (5 papers, 2013 to 2025). A primary or metastatic malignant neoplasm affecting the brain. "Like Th1 cells, Th2 cells can be synergistic in assisting anti-tumour CD8+ T cell responses, as shown by a study that examined co-infiltration of CD4+ phenotypes with CD8+ T cells in a model of brain cancer." (PMID 32451467, 2020).
chronic beryllium disease (5 papers, 2016 to 2025). Chronic beryllium disease (CBD) is a granulomatous, interstitial lung disease that occurs in individuals who develop beryllium sensitization (BeS), a cell-mediated immune response to environmental and occupational beryllium exposure. "Notably, this single mutation seems to drive helper CD4 T cells in susceptible individuals to secrete Th1-type cytokines, such as gamma-interferon, but not IL-4, leading to beryllium-induced hypersensitivity and chronic beryllium-disease." (PMID 27959918, 2016). "Previously, using a humanized model of chronic beryllium disease, we demonstrated a protective role of tissue-resident regulatory CD4+ T cells and B cells in CBD." (PMID 39935485, 2025). "CD4+ T cells drive the immunopathogenesis of chronic beryllium disease (CBD), and their recruitment to the lung heralds the onset of granulomatous inflammation." (PMID 35819849, 2022). "In chronic beryllium diseases, another lung granulomatosis, PD-1 expression on CD4+ T cells directly correlated with the severity of T-cell alveolitis." (PMID 36685602, 2022). "The TLR9 in DCs recognize phagocytosed self-DNA and induce the expansion of pathogenic CD4+Th1 cells recognizing beryllium-modified HLA-DP2/peptide complex (beryllium-specific CD4+T cells) before the clinical development of pulmonary granulomas characterizing chronic beryllium disease (CBD)." (PMID 33643304, 2020).
chronic gastritis (5 papers, 2021 to 2024). Inflammation of the stomach that is chronic in nature. "We know well that the prominent immune response in the early stages of chronic gastritis is made up of IFN-γ-producing CD4+ T-helper 1 cells (Th1s) and IL-17-producing CD4+ T-helper cells (Th17s)." (PMID 35757757, 2022). "Besides, this study proved that IL22+ CD4+ T cells and Foxp3+ Treg cells were positively correlated with H. pylori colonization and the severity of chronic gastritis." (PMID 36705412, 2023).
chronic tonsillitis (5 papers, 2014 to 2021). "Single-cell and spatial maps confirmed that CD68+ cells were correlated with the enhanced Granzyme B expression and CD3+ cells exhibited enrichment of CD4+ phenotype in chronic tonsillitis." (PMID 34045665, 2021). "The long-term memory GPR56+/CD4+ lymphocyte subsets likely expanded at the marginal zone of the lymphatic follicles of palatine tonsils with chronic tonsillitis." (PMID 33490647, 2021). "It is likely that the long-term CD4+ lymphocytes proliferate at palatine tonsils with chronic tonsillitis in both autocrine and paracrine manners." (PMID 33490647, 2021). "Moreover, further examination is necessary to understand the effects of the PD-1+/CD4+ lymphocytes on the elder immune system of PD-1-/CD4+ lymphocytes in patients with chronic tonsillitis." (PMID 33490647, 2021). "However, the effects of the PD-1+/CD4+ lymphocytes on the local immune system of PD-1-/CD4+ lymphocytes in the elder patients with chronic tonsillitis is not clearly understood." (PMID 33490647, 2021). "They reported high expression of PD-1 on CD4+ and CD8+ T cells in chronic tonsillitis patients, but this expression was significantly lower than in cancerous tonsils." (PMID 26319791, 2016).
classic Hodgkin lymphoma (5 papers, 2019 to 2025). Classical Hodgkin lymphoma (CHL) is a B-cell lymphoma characterized histologically by the presence of large mononuclear Hodgkin cells and multinucleated Reed-Sternberg (HRS) cells. "A recent study in Classic Hodgkin lymphoma (CHL) murine models demonstrated that PD-1 blockade therapy has strong anti-tumor effects on MHC-II expressing tumors mediated by cytotoxic CD4+ T cells." (PMID 33329566, 2020).
colonic polyps (5 papers, 2018 to 2024). "Conversely, Eubacterium brachy may reduce the risk of colon polyps by decreasing the levels of CD4 on CD28+ CD4+ T cells." (PMID 39346904, 2024). "Results reveal that expression of EpCAM and PD-L1 on CD4+ T cells significantly increased in patients with CC, compared with age- and sex- matching healthy controls and patients with colonic polyps." (PMID 31354723, 2019). "Additionally, Eubacterium brachy was a protective factor against colon polyps, with its mechanism of action being related to CD4 on CD28+ CD4+ T cells." (PMID 39346904, 2024). "When AOM-3DSS-induced colonic polyp-derived MHC-II−Gr1+ cells were co-cultured with splenic CD4+ T cells, T cell proliferation was suppressed by these tumor-infiltrating Gr1+ cells from WT mice, while Gr1+ cells from Clec7a−/− mouse polyps suppressed T cell population only weakly." (PMID 36932082, 2023). "To verify whether the identified population EpCAM+ CD4+ T cells increased in patients with benign polyps, we examine a cohort of patients with colonic polyps (CP) and determine their T cell subset landscape using the same mass cytometry staining panel above." (PMID 31354723, 2019). "Analysis of immune cell infiltrates in the colonic polyps showed significantly decreased CD8+ T cells and increased IL-17+ CD4+ and IL-17+ CD8+ T cells in Gpr15-KO than in Het mice." (PMID 38074634, 2023). "Interestingly, the colon polyps (LIP) in the AOM-DSS treated Gpr15-KO mice showed distinct (e.g., expansion of MDSCs) as well as shared (e.g., increased IL-17+ CD4+ and IL-17+ CD8+ T cells) immune features of human CRC with reduced GPR15 expression." (PMID 38074634, 2023). "Interestingly, the colon polyps (LIP) in the AOM-DSS treated Gpr15-KO mice showed distinct (e.g., increased MDSCs) as well as shared (e.g., increased IL-17A+ CD4+ and IL-17A+ CD8+ T cells) immune features of human CRC with reduced GPR15 expression." (PMID 38074634, 2023).
coronary atherosclerosis (5 papers, 2019 to 2025). Atherosclerosis of the coronary vasculature. "IL-32γ contributes to the development of coronary atherosclerosis by stimulating resident HIV-infected CD4+ memory T cells within cardiac tissue." (PMID 41383621, 2025). "Winchester reported significant increases in circulating CD4 + T cell subsets in RA patients with subclinical coronary atherosclerosis." (PMID 34915859, 2021). "CD4+/28CD–/CD57+ senescent T cells, which are associated with unstable atherosclerotic plaques and clinical coronary atherosclerosis are seen essentially only in IRP+ patients." (PMID 31507586, 2019).
Dengue hemorrhagic fever (5 papers, 2018 to 2025). A serious condition caused by Dengue virus infection. "A massive activation of adaptive immune cells, especially cross-reactive memory CD4+ T cells, has been reported to be a critical event in dengue hemorrhagic fever (DHF) pathogenesis." (PMID 33322218, 2020). "Dengue hemorrhagic fever showed a higher T cell:monocyte Ka for CD8+ over CD4+ cells whereas Tdap day three post boost showed the opposite, with highest Ka for CD4+ over CD8+ cells." (PMID 31237234, 2019). "In cases of dengue hemorrhagic fever in human children, increased numbers of CD69+ natural killer cells, CD4+ T cells, and CD8+ T cells have been observed." (PMID 29771921, 2018). "In subjects with active TB, the Ka between monocytes and CD4+CD8+ (DPOS) T cells or CD4+ T cells was significantly higher than for CD8+ T cells and both DPOS and CD4+ T cell:monocyte complexes had higher Ka in active TB compared to dengue hemorrhagic fever." (PMID 31237234, 2019). "In PBMCs from patients experiencing dengue hemorrhagic fever, flow cytometry analysis after nonspecific polyclonal stimulation demonstrated a strong immune response skewed toward IL-17 production, marked by a heightened occurrence of CD4+IL-17+ T cells." (PMID 39989460, 2025).
Duchenne muscular dystrophy (5 papers, 2021 to 2022). Duchenne muscular dystrophy (DMD) is a neuromuscular disease characterized by rapidly progressive muscle weakness and wasting due to degeneration of skeletal, smooth and cardiac muscle. "This has been reported in muscles in Duchenne muscular dystrophy (DMD) patients and mdx-mice, including T-lymphocytes (CD4, CD8 and regulatory T-cells or TRegs), natural killer (NK) cells, neutrophils, eosinophils and macrophages." (PMID 35563815, 2022). "The dichotomous role of inflammation has been extensively studied in Duchenne muscular dystrophy (DMD), in which CD4+ and CD8+ T cells, macrophages, eosinophils and natural killer T cells infiltrated both human and mouse dystrophic muscle." (PMID 35056146, 2022). "On this same vein is the action of such a reagent in impairing in vitro transendothial and fibronectin-driven migration of CD4+ and CD8+ T cells expressing high densities of VLA-4 from Duchenne muscular dystrophy patients, thus potentially enlarging the use of this strategy to other diseases." (PMID 35919739, 2021). "In contrast to polymyositis, Duchenne muscular dystrophy or Becker muscular dystrophy (DMD/BMD), CD4 T cell, macrophage, and membrane attack complex (MAC) are more highly expressed in muscles with dysferlinopathy." (PMID 36203997, 2022). "CD4+ and CD8+ T cells have also been associated with muscle degeneration and fibrosis in the mdx mice, a natural mutant that does not express dystrophin and Duchenne muscular dystrophy (DMD) homolog, by induction of specific antigen activation of CD44+ cells homing into the damaged tissue." (PMID 35740942, 2022).
duodenal ulcer (5 papers, 2012 to 2024). An ulcer in the duodenal wall. "Consistent with our results, omeprazole treatment increases the frequency of CD4+ CD25+ FoxP3+ Treg cells and decreases the frequency of CD4+ IL-17A+ T cells among peripheral blood mononuclear cells (PBMCs) of patients with duodenal ulcers." (PMID 39247190, 2024). "The first recipient analyzed (RA) was a 57-year-old male that received red blood cells from blood donor due to a bleeding duodenal ulcer and also evolved with a stable CD4 without a detectable emergency of X4 related strains from 1986 to 1991." (PMID 22768122, 2012).
enterovirus infection (5 papers, 2013 to 2021). "In contrast, FOXP3 expression was significantly decreased in highly activated (CD4+CD127−/loCD25+FOXP3high) regulatory T cells (TregFOXP3high) in the infants who had enterovirus infection during the preceding 30 or 60 days." (PMID 33643278, 2020). "These patients were HIV-1 positive with relatively low CD4 counts (0.18 and 0.05×10E9 cells/L in the two patients with enterovirus infection)." (PMID 24223808, 2013).
Erythema nodosum (5 papers, 2009 to 2023). An erythematous eruption commonly associated with drug reactions or infection and characterized by inflammatory nodules that are usually tender, multiple, and bilateral. "Consistent with the increased expression in skin lesions, the expression of IL-22 in the supernatants of stimulated PBMCs and the frequency of IL-22-positive CD4+ T cells in PBMCs from BD patients with erythema nodosum were also higher than the normal range." (PMID 23527071, 2013).
erythroleukemia (5 papers, 2013 to 2025). Acute erythroid leukemia characterised by the presence of at least 50% erythroid precursors and at least 20% myeloblasts in the bone marrow. "The results indicated that D-EDA significantly increased the expression of CD4, CD8a, and B220, suggesting enhanced immune cell activation and improved immune function in erythroleukemia mice." (PMID 40362240, 2025). "Moreover, the proportions of CD4, CD8a, and B220 cells in erythroleukemia spleen also increased significantly in the H-120 treatment group, indicating that H-120 effectively stimulates the immune cells in erythroleukemia mice." (PMID 38611876, 2024). "Specifically, FV-specific CD4 T cells were shown to mediate direct antiviral effects leading to reduced viral replication and reduced spread of FV to the erythroid lineage as well as to reduced induction of erythroleukemia." (PMID 23717308, 2013). "Consistent with a protective role of CD4 T cells, their in vivo depletion during acute infection promoted viral spread as well as onset of erythroleukemia and resulted in reduced maintenance of FV-specific CD8 T cells as well as neutralizing antibody responses." (PMID 23717308, 2013). "Moreover, this study further revealed that D-EDA alleviated the burden on the spleen and liver, restored spleen structure, enhanced the differentiation of Ter119+, CD4+, CD8a+, and B220+ cell populations, and effectively prolonged the survival of erythroleukemia mice in vivo." (PMID 40362240, 2025).
esophagitis (5 papers, 2021 to 2025). An acute or chronic inflammatory disease affecting the esophageal wall. "Interestingly, we found that selenium effectively reduced 4-NQO-induced esophagus inflammation by decreasing CD45, CD8, and CD4 T-cell markers in mice and the nuclear/cytoplasmic ratio of NF-κB in H2O2-treated human immortalized esophageal epithelial cell lines." (PMID 35628320, 2022).
hemochromatosis (5 papers, 2005 to 2025). A disorder of iron metabolism characterized by a triad of HEMOSIDEROSIS; LIVER CIRRHOSIS; and DIABETES MELLITUS. "Despite not being able to bind peptides, HFE was shown to affect the set-up of the T-cell repertoire and, in particular, the CD4/CD8 ratio, which was found to be unbalanced in hemochromatosis patients carrying HFE mutations." (PMID 38003490, 2023).
HIV-associated nephropathy (5 papers, 2013 to 2024). Renal disease in human immunodeficiency virus (HIV)-infected patients. "Glomerular disease is the predominant representation of HIV-related renal injury, particularly through HIV-associated nephropathy (HIVAN), which occurs at high viral loads and low CD4+ T-cell counts." (PMID 36233315, 2022). "ARTswitched cases ultimately had lower CD4 counts and significantly higher creatinine, thus pointing to possible cases of HIV nephropathy." (PMID 28931037, 2017).
HTLV infection (5 papers, 2011 to 2023). "In HTLV infection, the upregulation of PD-L1 on CD4+ and CD25+ T cells, as well as the upregulation of PD-1 on CD8+ T cells (especially HTLV-1-specific T cells) together with anti-virus T cell dysfunctions have been reported." (PMID 21943148, 2011).
hyper-IgE syndrome (5 papers, 2013 to 2025). A condition that is characterized by elevated serum IgE, dermatitis, and respiratory infections. "Its deficiency results in impaired Th17 differentiation from naïve CD4+ T cells, contributing to the AR hyper-IgE syndrome (HIES), or Job syndrome." (PMID 40649913, 2025). "As shown by studies in hyper-IgE syndrome (HIES) patients, the loss-of-function mutations of STAT3 abrogates the DC responsiveness to IL-10 and thereby impairs their tolerogenic functions and ability to stimulate differentiation of CD4+ T cells to regulatory T cells (Tregs)." (PMID 29921770, 2018).
hyperhomocysteinemia (5 papers, 2016 to 2023). A serious metabolic condition caused by mutations in the MTHFR gene, medications, or nutritional deficiency. "A previous report indicated that shikonin attenuates hyperhomocysteinemia‐induced activation of CD4+ T cells in ApoE−/− mice." (PMID 34646528, 2021). "Demonstrating the importance of 1,25(OH)2D3-VDR signaling for BHMT1 enzyme activity in CD4+ T cells, we found that mice with CD4+ T cell-specific Vdr gene targeting developed hyper-homocysteinemia (HHcy) when they were immunized to induce EAE." (PMID 32528735, 2020).